CDC14B (cell division cycle 14B)
Description:
Dual-specificity phosphatase involved in DNA damage response. Essential regulator of the G2 DNA damage checkpoint: following DNA damage, translocates to the nucleus and dephosphorylates FZR1/CDH1, a key activator of the anaphase promoting complex/cyclosome (APC/C). Dephosphorylates SIRT2 around early anaphase. Dephosphorylation of FZR1/CDH1 activates the APC/C, leading to the ubiquitination of PLK1, preventing entry into mitosis. Preferentially dephosphorylates proteins modified by proline-directed kinases.
Synonyms: Cdc14B1; Cdc14B2; CDC14B3; hCDC14B
Tractability: No criterion of Open Targets' tractability assessment is met for any kind of drug.
Target class: Enzyme; Hydrolase
Gene: Protein-coding gene on chromosome 9 (96,490,241 to 96,619,855, reverse strand). Ensembl gene ENSG00000081377.
Subcellular location: Nucleus, nucleolus; Nucleus, nucleoplasm
Subcellular location (Human Protein Atlas): Nucleoplasm; Cell Junctions; Cytosol
Pathways (Reactome):
Signal Transduction: MAPK6/MAPK4 signaling
Gene Ontology:
Molecular function: protein binding; protein serine/threonine phosphatase activity; protein tyrosine phosphatase activity
Biological process: mitotic G2 DNA damage checkpoint signaling; positive regulation of ubiquitin protein ligase activity; protein dephosphorylation; cilium assembly; microtubule cytoskeleton organization; positive regulation of cytokinesis; regulation of exit from mitosis
Cellular component: nucleolus; nucleoplasm; nucleus; cytoplasm; mitotic spindle; spindle pole
Genetic constraint (gnomAD): Loss-of-function variants: 5 observed, 20 expected, observed/expected ratio (o/e) 0.25, 90% interval 0.13 to 0.53. The upper end of that interval is the gene's LOEUF score, 0.53, which puts it in group 2 of 6, group 1 being the genes least tolerant of losing a copy. Missense variants: 250 observed, 287.5 expected, observed/expected ratio (o/e) 0.87, 90% interval 0.78 to 0.97. Synonymous variants: 100 observed, 100.14 expected, observed/expected ratio (o/e) 1, 90% interval 0.85 to 1.18.
Homologues: Orthologues: chimpanzee CDC14B (100% identical), macaque CDC14B (99% identical), rat Cdc14b (88% identical), mouse Cdc14b (85% identical), dog CDC14B (84% identical), guinea pig Cdc14b (73% identical), tropical clawed frog cdc14b (57% identical), zebrafish cdc14b (51% identical). Paralogues in human: CDC14C (81% identical), CDC14A (53% identical), PTPDC1 (17% identical), PALD1 (14% identical), PTP4A1 (11% identical), PTP4A2 (10% identical), PTP4A3 (10% identical), CDKN3 (9% identical).
Diseases named in the same sentence as CDC14B in open-access papers:
CDC14B is named in the same sentence as 16 diseases in open-access papers, as found by Europe PMC text mining. Sharing a sentence is not in itself a finding about the gene and the disease. The quoted sentences say what the papers report.
glioblastoma (5 papers, 2015 to 2025). The most malignant astrocytic tumor (WHO grade IV). "For instance, ADAR2 targets intronic Alu elements of phosphatase cell division cycle 14B (CDC14B), an upstream regulator of S-phase kinase-associated protein 2 (Skp2)/p21/p27 pathway, in glioblastoma (GBM)." (PMID 39126156, 2025). "Overall, these data indicate the essential role of ADAR2 editing in glioblastoma, acting on multiple targets (CDC14B, pri-miR-221/222, pri-miR-21, miR-376a-5p, GRIA2) that together contribute to varying extents to cancer progression." (PMID 26437436, 2015). "Moreover, we recently demonstrated that ADAR2 deaminase activity is sufficient to inhibit glioblastoma proliferation and tumor growth, as it modulates the CDC14B/Skp2/p21/p27 pathway in adult glioblastoma cell lines and this was further confirmed in different grades of pediatric glioma." (PMID 25582055, 2015). "The phosphatase CDC14B, which acts upstream of the Skp2/p21/p27 pathway, is a critical ADAR2 target involved in glioblastoma growth." (PMID 26437436, 2015).
glioma (4 papers, 2020 to 2024). A benign or malignant brain and spinal cord tumor that arises from glial cells (astrocytes, oligodendrocytes, ependymal cells). "As ADAR2 activity decreases in gliomas, CDC14B pre-mRNA modification is decreased, resulting in overexpression of Skp2 and downregulation of the known tumor suppressors p21 and p27." (PMID 32375856, 2020). "In other studies, the activity of ADAR2 was deemed essential to prevent glioma proliferation and growth through the editing of the CDC14B pre-mRNA transcript involved in the Skp2/p21/p27 pathway." (PMID 32375856, 2020). "In glioma, aberrant expression of ADARB1 can affect the proliferation and invasion of glioma cells by regulating microRNAs or CDC14B-Skp2 signaling axis." (PMID 35004651, 2021).
astrocytoma (2 papers, 2018 to 2025). "ADAR2 promotes CDC14B editing and overexpression in astrocytoma cells, leading to Skp2 degradation and upregulation of p21 and p27 proteins, consequently causing cells to accumulate in the G1 phase of the cell cycle." (PMID 30524204, 2018).
astroglioma (1 paper, 2022). "MiR-1247-5p exerts a tumor suppressor effect in human astroglioma cells by targeting CDC14B." (PMID 36090902, 2022).
cataract (1 paper, 2011). Partial or complete opacity of the crystalline lens of one or both eyes that decreases visual acuity and eventually results in blindness. "When Cdc14b-deficient mice were left to age, they develop cataracts and kyphosis at early ages, suggesting a role of Cdc14b in preventing the early onset of aging." (PMID 21666283, 2011).
cervical cancer (1 paper, 2021). A primary or metastatic malignant neoplasm involving the cervix. "RP11-384K6.2 is regulated by hsa-miR-657, which was found to have tumor-associated putative target genes that were associated with cervical cancer, including CDC14B, TNFSF11 and PTPN245." (PMID 33403041, 2021).
invasive breast carcinoma (1 paper, 2020). A carcinoma that infiltrates the breast parenchyma. "The gene expressions of ACOT7, STAT1, TYMP, and VOPP1 were significantly increased in invasive breast carcinoma, while the gene expressions of ACTG2, CNN1, CDC14B, NFIB, RCN1, and TRIM2 were dramatically downregulated in BRCA." (PMID 31986487, 2020).
male infertility (1 paper, 2020). The inability of the male to effect fertilization of an ovum after a specified period of unprotected intercourse. "The paralogue CDC14B may compensate for the loss of some CDC14A functions in vivo, but does not compensate for male infertility and hearing impairment with loss of CDC14A." (PMID 31906439, 2020).
papillary thyroid cancer (1 paper, 2017). "We found a significant association between the localization of RET mutations and the expression of three genes: NNAT (suggested to be a tumour suppressor gene), CDC14B (involved in cell cycle control) and NTRK3 (tyrosine receptor kinase that undergoes rearrangement in papillary thyroid cancer)." (PMID 28181547, 2017).
tumor (13 papers, 2015 to 2025). "At the same time, CDC14B is deleted or mutated in different tumor entities, suggesting tumor-suppressive functions." (PMID 32152317, 2020). "The editing process that ADAR2 mediates increases the expression of CDC14B, which in turn lowers Skp2 levels and promotes tumor suppression." (PMID 40852728, 2025). "ADAR2 functions as a tumor suppressor by editing targets, such as CDC14B, and modulating the miRNA network to restrain cell cycle progression and migration." (PMID 40852728, 2025). "In GBM, ADAR2 exerts clear tumor suppressor roles through editing targets such as CDC14B and regulating miRNAs, reducing cell proliferation and migration." (PMID 40852728, 2025). "In GBM, loss of ADAR2 editing of CDC14B leads to an increase in Skp2 signaling and increased tumor growth, but this growth is inhibited with the addition of edited CDC14B transcripts ⁠." (PMID 40362314, 2025). "This mechanistic cascade (CDC14B/Skp2/p21/p27 axis) illustrates a clear pathway by which ADAR2 editing activity constrains tumor cell growth." (PMID 40852728, 2025). "ADAR2 editing modulates CDC14B/Skp2/p21/p27 axis, suppressing tumor progression." (PMID 40852728, 2025). "The role in the tumour transformation ability of CDC14B gene is controversial." (PMID 28181547, 2017). "For example, ADAR1 promotes tumor progression in melanoma and TNBC by evading the immune system and suppressing IFN signaling, while ADAR2 exhibits tumor-suppressive roles in GBM and liver cancer by editing transcripts such as COPA and CDC14B." (PMID 40852728, 2025). "Interestingly, genes with oncogenic potential, including CDC42, CDC14B, STK40, BRD3, CPNE1, and MCM3, were downregulated, whereas tumor inhibitors, including CDKN2C, CASP7, and CDKN1B, were upregulated by RBM15 depletion." (PMID 38825643, 2024).
cancer (1 paper, 2024). A tumor composed of atypical neoplastic, often pleomorphic cells that invade other tissues. "Although we focused on RBM15 and serine metabolism in this study, network analysis revealed that the relationship between RBM15 and other genes with oncogenic potential (CDC42, CDC14B, STK40, BRD3, CPNE1, and MCM3) is also crucial for cancer cell survival." (PMID 38825643, 2024).
CDC14B also shares sentences with these, for which no sentence is quoted: Azoospermia (1 paper); colon cancer (1); colorectal carcinoma (1); infection (1); medullary thyroid cancer (1).